ID1 (inhibitor of DNA binding 1)
Diseases named in the same sentence as ID1 in open-access papers (continued):
Sharing a sentence is not in itself a finding about the gene and the disease.
cancer (continued). "In several of these cancer types, overexpression of Id1 is associated with an aggressive phenotype and poor clinical outcome." (PMID 20414347, 2010). "Id-1 mediated cancer cell growth has been shown to be associated with EGFR activation in ovarian and prostate cells." (PMID 19014499, 2008). "An overexpression of ID1 was associated with several cancers and cancer-associated pathways." (PMID 34026614, 2021). "Moreover, the downregulation of XOR in cancer cells is associated with an increased expression of two important factors, the inhibitor of differentiation 1 (ID1) and cyclooxygenase 2 (COX-2)." (PMID 34588926, 2021). "Additionally, gene ID1 expression was evaluated because of its association with cancer progression in several cell models." (PMID 32244518, 2020). "To explore the mechanism of ID1 that induces chemoresistance, we first detected the cellular autophagy because the recent studies have shown that cancer cell chemoresistance may be associated with autophagy." (PMID 32080166, 2020). "As a result, the data showed that ID1 regulated angiogenesis supported by arsenic, and ID1 may be an anti-angiogenesis target for cancer associated with arsenic." (PMID 30634536, 2019). "On the other hand, it has been pointed out that LMP1 onco-protein of EBV upregulates Id-1 expression in nasopharyngeal immortalized and cancer cells; however, the association between EBV onco-proteins and Id-1 in human carcinomas, including cervical is not clear." (PMID 30035100, 2018). "Considering that high levels of ID protein expression in cancer cells are important, potential prognostic and diagnostic markers in several tumors, including breast, colorectal, liver, and prostate cancers, the treatment strategy of targeting ID1 in CSCs is a promising way to cure cancer." (PMID 30455990, 2018). "In cancer cells MCAM has been linked with Id1 expression, which is a known inhibitor of myogenesis." (PMID 28923978, 2017). "Constant deregulation of Id1 and Id3 has been implicated in a wide range of carcinomas." (PMID 25061504, 2014). "Moreover, it has been suggested that ID1 was associated with cancer stemness." (PMID 37607071, 2023). "Therefore, maintaining cancer stemness might be the underlying mechanism that TCF3 transcriptionally regulated ID1 and further promoted ESCC progression and drug resistance." (PMID 37607071, 2023). "Evidence indicates that Id-1 may be associated with an aggressive phenotype of human cancers." (PMID 15026801, 2004). "Therefore, it remains unclear whether Id-1 has a proliferative potential in human primary cancers although Id-1 has been implicated in the modulation of several cell cycle regulators." (PMID 15026801, 2004). "With our in vitro assays demonstrating that high expression of ID1 promotes VM, we next investigated if ID1 expression varied during cancer progression." (PMID 40116596, 2025). "More specifically, reducing ID1 lowered cancer cell expression of endothelial cell genes (e.g. CDH5, TIE2) and production of pro‐angiogenic proteins (e.g. VEGF, CD31, MMP9 and IL‐8)." (PMID 40116596, 2025). "Our work supports further development of anti‐ID1 reagents with the proposed impact directly on cancer cells for inhibition of VM and reduction of disease progression." (PMID 40116596, 2025). "In silico analysis of MDA‐MB‐231 cells engrafted into mice identified elevated ID1 expression in cancer cells that had metastasised to the lungs or liver, and an enrichment of pro‐angiogenic genes." (PMID 40116596, 2025). "Our observation of ID1 regulating MMP9 secretion is of interest in cancer progression as it degrades the extracellular matrix and basement membrane components to promote cancer metastasis." (PMID 40116596, 2025). "With building evidence that elevated levels of ID1 in cancer cells also contribute to chemotherapy and radiotherapy resistance, controlling ID1 expression and/or function warrants further investigation." (PMID 40116596, 2025).
cancer (continued). "It is our contention that ID1 is a strong regulator of DKK‐1 in cancer cells and implicates known VM pathways (P13K/AKT and ERK) to promote extracellular matrix (ECM) remodelling and ultimately VM formation." (PMID 40116596, 2025). "Elevated expression of transcriptional regulator inhibitor of DNA binding 1 (ID1) promoted cancer cell‐mediated vasculogenic mimicry (VM) through regulation of pro‐angiogenic and pro‐cancerous genes (e.g. VE‐cadherin (CDH5), TIE2, MMP9, DKK1)." (PMID 40116596, 2025). "Taken together, these results support our contention that ID1 facilitates VM by cancer cells to assist disease progression." (PMID 40116596, 2025). "Our observations further implicate ID1 in cancer progression as a master regulator of VM by cancer cells and mediator of lung and liver metastases." (PMID 40116596, 2025). "Taken together, this study further implicates ID1 in a vascular program within cancer cells that supports disease progression." (PMID 40116596, 2025). "Next, we explored the potential contribution of Id1 to the acquired resistance to trametinib-mediated apoptosis, a core mechanism of trametinib-mediated cancer cell death, in TR KRAS-mutant mouse and human LUAD cells." (PMID 38643157, 2024). "Inhibitor of differentiation/DNA binding 1 (ID1), a member of the helix-loop-helix protein family, has been documented to have pro-oncogenic properties, encouraging both proliferation and cancer metastasis." (PMID 38183094, 2024). "The transcriptional regulatory protein, an inhibitor of DNA-binding-1 (ID-1), is a key regulator of cell phenotype in cancer." (PMID 39455562, 2024). "ID1 overexpression has been found in various cancers, and it has been identified as a prognostic predictor of lymph node metastasis and reduced survival in patients with penile cancer." (PMID 38157850, 2024). "To explore the association between ID1 and ID3 expression and overall survival, we utilised data from the TARGET Pan-Cancer cohort available in the TCGA database, focusing on B-ALL." (PMID 39676870, 2024). "Suppressing USP1 leads to the degradation of the ID1 transcription factor, crucial for cancer progression." (PMID 38534787, 2024). "Smad-1/5-dependent signaling includes the transcriptional activation of inhibitor of differentiation proteins (ID1–3), which regulate cancer cell metastasis and stemness of cancer stem cells." (PMID 39315260, 2024). "For example, the activation of mitogen-activated protein kinase (MAPK) signaling has been demonstrated as a mechanism of ID1-induced cancer cell proliferation." (PMID 39052126, 2024). "Numerous studies have reported that ID1 exerts a crucial effect in cancer initiation and development." (PMID 37964494, 2024). "Orai3 promotes cancer stem-like cell phenotypes by upregulating the stemness transcription factor ID1, suggesting that the Orai3/ID1 axis is a novel regulatory mechanism for maintaining cancer stemness in OSCC." (PMID 39759147, 2024). "This suggests that the Orai3/ID1 axis is a novel regulatory signaling mechanism for maintaining cancer stemness in OSCC." (PMID 37759448, 2023). "High ID1 expression in TAMs represents an immune evasion and cancer stemness-maintaining mechanism in CRC." (PMID 37996458, 2023). "Our above data indicated that the secretory components regulated by ID1 are crucial for TAMs in maintaining cancer stemness and promoting cancer immune invasion." (PMID 37996458, 2023). "ID1 is highly expressed in a variety of human cancer types, such as colon, ovarian, pancreatic, esophageal cancers and glioblastoma." (PMID 37996458, 2023). "Of all the ID proteins, ID1 is extensively studied and mostly linked to cancer malignant behavior and poorer prognosis." (PMID 37607071, 2023). "In mechanism, elevated expression of TCF3 in cancer cells led to the upregulation of Inhibitor of DNA binding 1 (ID1) and finally promoted ESCC cell growth by inducing cancer stemness and enhancing the expression of CD44 and CD133." (PMID 37607071, 2023).
cancer (continued). "In the ONCOMINE database, the mRNA expression of ID1 was up-regulated in many cancers, including CRC." (PMID 37373188, 2023). "Genetic inhibition of ID1 in OSCC cells suppressed cancer stemness features, including self-renewal and migration." (PMID 37759448, 2023). "This underscores an innovative regulatory mechanism for cancer stem cells involving the Orai3/ID1 axis." (PMID 37759448, 2023). "In conclusion, our study indicates that TCF3 has an important function in the development of ESCC and reveals that TCF3 regulates the cancer progression by activating cancer stemness induced by ID1." (PMID 37607071, 2023). "Recently, we detected that, during the malignization of cancer cells, the opposite effect occurred—the simultaneous extreme upregulation of three ID genes: ID1, ID2, and ID3 (paper in preparation)." (PMID 37372991, 2023). "Our study reveals that Orai3 is a novel functional CSC regulator in OSCC and further suggests that Orai3 plays an oncogenic role in OSCC by promoting cancer stemness via ID1 upregulation." (PMID 37759448, 2023). "In this study, for the first time, we demonstrated that 5-demethyl NOB inhibits cancer cell proliferation, suppresses the gene expression of ID1, regulates the NF-κB pathway, and exerts antileukemic effects in human AML cells." (PMID 35806401, 2022). "ID1 levels in human PDAC cancer cells were dramatically increased compared to normal epithelial cells." (PMID 35941362, 2022). "In our recent study, we demonstrated that elevated BMP9 expression is associated with poorer HCC prognosis and that BMP9 promotes EpCAM-positive cancer stem cell properties in HCC by inhibiting DNA-binding protein 1 (ID1)." (PMID 35163396, 2022). "To further confirm that, we quantified the percentage of the epithelial/cancer cells with Id1 transcription at Id1 > 1 and found a gradual increased percentage along with the progression of PDAC." (PMID 35941362, 2022). "Of these genes, we explored one gene, ID1, that has multiple prior published reports in other cancer types related to RR." (PMID 36627902, 2022). "TGF-β1 suppresses ID1 (inhibition of differentiation) in normal cells, but promotes ID1 in cancer cells." (PMID 35200587, 2022). "MYC actively represses ZNF148 expression, and in turn, the depletion of ZNF148 leads to de-repression of ID1/3, which drives the cancer stem cell phenotype." (PMID 36207293, 2022). "LMO2-driven activation of STAT3 signaling requires the LDB1 protein and leads to increased expression of an inhibitor of differentiation 1 (ID1), a master regulator of cancer stemness." (PMID 35805116, 2022). "ID1 expression marked the heterogeneity of human PDAC cancer cells and the relative expression levels were correlated with the malignance of PDAC cancer cell clusters." (PMID 35941362, 2022). "This likely occurs in cancers when a high TGFβ signal disrupts Nur77-mediated ID1 interaction with and ubiquitylation by Smurf2." (PMID 33990575, 2021). "This hypoxia-dependent reduction of ID1 protein was present in a variety of cancer cell lines (prostate, liver, and brain) that express detectable levels of endogenous ID1." (PMID 34820369, 2021). "TGFβ can stabilize not only basal and its own-induced ID1 but also ID1 induced by other signals, thus serving as a mechanism for the interplay between TGFβ and other signals for promoting cancer progression." (PMID 33990575, 2021). "First, TGFβ can efficiently increase ID1 expression in cancer cells through both mRNA induction and protein stabilization." (PMID 33990575, 2021). "ID1, a potent promoter of cancer growth, metastasis, and stemness, represents an attractive drug target for cancer treatment." (PMID 33990575, 2021). "Id1 is overexpressed in numerous types of cancers and exerts its promotion effect to these tumors through different pathways." (PMID 32410828, 2020).
cancer (continued). "Immunohistochemistry (IHC) analysis revealed that ID1 is expressed by a small minority of cells (range 0.5–6% of total cancer cells) in ~50% of ER-negative disease, namely TNBC and Her2+ tumors." (PMID 32766238, 2020). "ERβ binds with Id1 protein, whilst removing Id1 inactivation of p21 expression, resulting in decreased cancer cell growth." (PMID 32944243, 2020). "By using gene overexpression or silencing, luciferase assay and human specimens, we show that ID1 induces high autophagy and confers cancer cell chemoresistance." (PMID 32080166, 2020). "Among these, ID1 is overexpressed in several cancers, such as colon, pancreatic, breast and brain cancers." (PMID 32354135, 2020). "These small-molecule inhibitors therefore promote degradation of ID1, a prime therapeutic target, and require further preclinical assessment to determine their efficacy for cancer therapy." (PMID 32354135, 2020). "The Id1 represent an interesting target for this purpose, as it is involved in cellular key events related to tumorigenesis and cancer progression." (PMID 32410828, 2020). "Id1 is widely expressed in a variety of human cancers and inhibits cell differentiation, promotes the occurrence, and development of cancers." (PMID 32974175, 2020). "Other mutational signatures including SBS40, SBS5, ID9, ID1 and ID2 were also enriched in BRCA1/2-mutated cancers expressing high levels of wild-type POLQ." (PMID 32885167, 2020). "This review will focus on the research progress of Id1 in the context of cancer and its treatment over the past decade." (PMID 32410828, 2020). "This means the effect of Id1 in the development of cancer is complicated, its role in the primary foci of cancer, the shedding and colonization of cancer cells, and the metastatic cancer needs further studied." (PMID 32410828, 2020). "Network analysis indicates that Id1 promotes cancer morphology, cell cycle and epithelial to mesenchymal transition by influencing AP1, tnf, tgfbeta, PdgfBB and estradiol pathways." (PMID 32410828, 2020). "Id proteins (mainly Id1 and Id3) have been demonstrated to be overexpressed in human cancers, including lung primary tumors." (PMID 33126649, 2020). "ID1 protein has been reported in actively proliferating cells and has been identified in more than 20 tumorigenic cancer types." (PMID 32244518, 2020). "In this study, we evaluated the effect of using two different subfragments of rVAR2, DBL1-ID2a and ID1-ID2a, for cancer cell isolation." (PMID 32244341, 2020). "ID1 has multiple roles in cancer progression, such as implantation in primary and metastatic niches, angiogenesis, CSC survival, chemoresistance, growth, apoptosis inhibition and activation of WNT signaling." (PMID 30899759, 2019). "This point is further supported by the data that p38 inhibition and water eluate produce a synergic inhibitory effect on the expression of ID1, ectopic expression of which we found significantly reversed cancer cells growth." (PMID 31777585, 2019). "ID1 constitutive expression determines neo-angiogenesis, survival, anti-apoptosis and invasion/migration, both in cancer and embryo development." (PMID 30899759, 2019). "Taken together, this study fractionizes dark tea according to the functional relevance to cancer cells growth, and demonstrates that ID1 would be a pivotal downstream effector that mediates the cell growth-inhibitory effects from water eluate fraction." (PMID 31777585, 2019). "Further, the low postnatal expression of Id-1 and its high expression in cancer stem cells mark them as attractive targets for anti-cancer therapy." (PMID 31250351, 2019). "The ID family member ID1 has also been found to be dysregulated in cancer and to direct multiple hallmarks of cancer, such as cell growth and survival, invasion and migration, and angiogenesis." (PMID 31602000, 2019).
cancer (continued). "Using a 1% cutoff for positivity, Id-1 protein expression was observed in 41/44 cases (93%); diffuse and strong Id-1 expression (>50% cancer cells positive) was predominantly observed in high-grade (poorly differentiated) carcinomas." (PMID 30035100, 2018). "More specifically, Id-1 protein expression is directly involved in cancer initiation and/or progression in different types of human malignancies including cervical." (PMID 30035100, 2018). "Id1 and Id3 proteins are overexpressed in a variety of human cancers, and play critical roles in cancer development and progression." (PMID 30297743, 2018). "Consistent with earlier studies, this study indicated that PA increase is associated with up-regulation of ID1, ID2, and ID3 mRNA expression and therefore inhibition of cancer cell differentiation." (PMID 30455990, 2018). "Bone morphogenic protein 2 (BMP2), another cytokine from the TGFβ family, positively affects Id1 gene expression in myoblasts, osteoblast-like cells, breast and lung cancer cells." (PMID 28122577, 2017). "Previous studies have demonstrated that Id-1 is suggested to play a critical role during invasion and metastasis in various cancers." (PMID 29233161, 2017). "While there are many studies about the role of Id1 in cancer development and progression, much less is known about the Id1 isoform generated by alternative splicing." (PMID 28122577, 2017). "The function of Id4 has been identified as a paradigm shift compared with Id1-3 in different tissues during development and in cancer." (PMID 28974640, 2017). "Increasing evidence has demonstrated that Id-1 is involved in the regulation of cancer cell proliferation." (PMID 29233161, 2017). "Taken together, these studies indicate that suppressed KLF17 in human cancers promotes metastasis through inducing ID1." (PMID 26662959, 2016). "ID1 protein is frequently overexpressed in over 20 types of cancer, supporting its role in the tumorigenesis of a wide range of tissues." (PMID 27582276, 2016). "The BMP signaling pathway is a potent direct regulator of the transcription of Id1, Id2, and Id3 during development as well as in cancer cells." (PMID 27048361, 2016). "Id1 also interacts with various genes, such as c-Myc and hypoxia-inducible factor-1 (HIF-1), that have been linked to cancer due to their effects on cell growth and metabolism." (PMID 27071670, 2016). "Elevated levels of ID1 protein have been reported in a variety of human cancers and are capable of promoting invasion and metastasis." (PMID 26662959, 2016). "In fact, Sema3c, Id1, Cxcl1 and Ctgf, which are upregulated in a variety of cancer types, were downregulated upon Pdrg1 silencing." (PMID 27548429, 2016). "On the other hand, the expression of ID1 is significantly correlated with high grade and poor prognosis of human cancer." (PMID 26662959, 2016). "Our mechanistic study provides an insight to the well-known observation that both KLF17 and TGF-β/Smad3 can regulate ID1 and impinge on cancer cell metastasis." (PMID 25766320, 2015). "Our observations confirm and extend the promise of Id1 as a biomarker of cancer progression and as a therapeutic target in the management of advanced malignancies." (PMID 25924227, 2015). "Blocking the expression of ID1 has been shown to decrease VEGF-A expression and hence angiogenesis during tumorigenesis, and ID inhibitors are being explored as novel therapies for cancers." (PMID 26577912, 2015). "ID1 is a synthetic sick/lethal gene that interacts with R175H and is considered to be a novel molecular target for cancer therapy in R175H-expressing cells." (PMID 24378760, 2014). "With respect to its role in the development and maintenance of cancers, Id1 overexpression is seen in a variety of solid tumors and appears to affect a number of cellular processes associated with malignancies." (PMID 24659686, 2014).